NOX1 (NADPH oxidase 1)
Diseases named in the same sentence as NOX1 in open-access papers (continued):
Sharing a sentence is not in itself a finding about the gene and the disease.
diabetes (continued). "Taken together, these studies have identified Nox-1 as a potential therapeutic target in the prevention of cytokine-induced islet dysfunction in diabetes." (PMID 33255484, 2020). "Several NOX families have been identified, including NOX1-7, of which NOX1, 2, and 4 activity are altered by diabetes, or diabetic complications." (PMID 30744045, 2019). "In the whole myocardium, NOX1 expression was unchanged by diabetes except in the GTE-enriched group where it was reduced (−56%, p < 0.05)." (PMID 31690052, 2019). "AGE/RAGE signaling has been shown to increase oxidative stress to promote diabetes-mediated vascular calcification through activation of Nox-1 and decreased expression of SOD-1." (PMID 27547766, 2016). "The expression of NADPH oxidase isoforms Nox1 and Nox2 was increased in diabetes and significantly reduced by high dose SGLT2i therapy." (PMID 25402275, 2014). "Among these, NOX1 plays a pivotal role in diabetes-induced atherosclerosis." (PMID 40725037, 2025). "In Apoe+ mice with STZ-induced diabetes, genetic deletion of Nox1 or pharmacological inhibition using GKT137831 (setanaxib, a dual NOX1/NOX4 inhibitor) significantly reduced atherosclerotic burden, as evidenced by decreased plaque area and improved plaque morphology." (PMID 40076813, 2025). "Moreover, the upregulation of ET-1 has been found to accelerate the progression of atherosclerosis, perivascular OS, and inflammation through NOX1 in diabetes." (PMID 39064844, 2024). "In recent years, the two most promising approaches to limiting the damage of the oxidative heart caused by diabetes are to inhibit NADPH oxidation by pharmaceutical activation of NRF2 and combined NOX1/NOX4 inhibitor GKT137831, as demonstrated in several preclinical models of diabetes." (PMID 37468902, 2023). "NOX1 contributes to macrovascular complications in diabetes and metabolic disease." (PMID 34849611, 2022). "This review describes the key roles of Nox2 and Nox4, as well as Nox1 and Nox5, in glucose homeostasis, endothelial function and oxidative stress, with a key focus on how they are regulated in health, and dysregulated in type 2 diabetes mellitus." (PMID 34571964, 2021). "Similarly, in a diabetes-accelerated model of atherogenesis, deletion of Nox1 in ApoE knockout mice demonstrated reduced levels of vascular ROS production and were strongly protected from vascular inflammation and plaque development." (PMID 33396868, 2020). "Lower lipid peroxidation was also seen in Nox1 knockout mice with diabetes and liver fibrosis." (PMID 32635630, 2020). "NOX-1 is stimulated by inflammatory cytokines that are elevated in diabetes." (PMID 23565109, 2013). "These compounds could have an important role in assessing a disruption of NOX-1/ROS signaling as a new approach to preserve and protect beta cell mass in diabetes." (PMID 23565109, 2013). "Conversely, the induction of three genes, Nox1, Nox4, and Txnip, by diabetes plausibly contributes to pathology by producing oxidative stress, and the complete reversal of the elevation of these genes by the ketogenic diet plausibly contributes to the reversal of neuropathy." (PMID 21533091, 2011). "Moreover, deletion of Nox1 in mice attenuates angiotensin II-induced aortic aneurysm formation, which may however, differ from the diabetes-dependent mechanism." (PMID 35798762, 2022). "Thus, the NOX1 level in atherosclerotic lesions in both humans and rabbits was shown to be extremely low, while its overexpression was observed in patients with cardiovascular disease or the development of diabetes mellitus." (PMID 32664404, 2020). "Distinct roles of NOX1 and NOX4 in modulating immune cell composition and VSMC morphology within atherosclerotic plaques in diabetes have been demonstrated in later studies." (PMID 40076813, 2025).
diabetes (continued). "Through the activation of Nox-1 and the reduced expression of Superoxide Dismutase-1 (SOD-1), AGE-RAGE signaling has been demonstrated to enhance oxidative stress and accelerate diabetes-related vascular calcification." (PMID 35956419, 2022). "Through the activation of Nox-1 and the decreased expression of SOD-1, AGE/RAGE signaling has been demonstrated to increase oxidative stress and promote diabetes-related vascular calcification." (PMID 35458596, 2022). "In the ex vivo study, a high D-glucose concentration upregulates NOX1 and NOX2 subtypes, whereas these NOXs relate to the pathology in vascular smooth muscle cells from patients with type 2 diabetes mellitus similarly." (PMID 34440716, 2021). "Administration of the dual Nox1/Nox4 inhibitor, GKT137831, in mice models upon induction of diabetes has been shown to attenuate the diabetes induced increases in atherosclerotic plaque area." (PMID 33396868, 2020). "Given that NOXO1 and p47phox are the organizer subunits for NOX1 and NOX2, respectively, and p47phox also binds NOX1, it was postulated that abolishing the action of one NOX subunit in diabetes would lead to compensatory upregulation of the counterpart." (PMID 31382355, 2019). "Therefore, NOX1 activation in diabetes may also be related to an immunological response." (PMID 31382355, 2019). "This was substantiated by the cellular co-localization of B1R with NOX1 and NOX2 and opens the possibility that B1R-enhanced oxidative stress is derived from vascular and infiltrating immune cells in diabetes." (PMID 29163205, 2017). "Because of their marked enhanced activities, NOX1 and NOX2 represent the most important superoxide-generating enzymes in diabetes and vascular disease." (PMID 29163205, 2017). "Improvement of renal function by Nox1/4 inhibitor was illustrated in an animal-model of diabetes that was independent of glucose control." (PMID 29682485, 2017). "Overall, these studies demonstrated that cell isolates from a model diabetes with VDN mediated vascular calcification model were respondent to AGE treatments as evidenced by significantly increased levels of ALP, ROS, Nox-1, and RAGE protein when compared to only diabetic animals." (PMID 27547766, 2016). "Likewise, NOX1 and NOX4 were found to be over-expressed in db/db diabetic mice, indicating that the NOX1 and NOX4 isoforms may exert a potential role in diabetes-related macrovascular disease." (PMID 34205998, 2021). "Diabetes did not change expression of Nox1 or catalase in mesenteric arteries." (PMID 32009974, 2019).
endothelial dysfunction (33 papers, 2017 to 2026). In vascular diseases, endothelial dysfunction is a systemic pathological state of the endothelium (the inner lining of blood vessels) and can be broadly defined as an imbalance between vasodilating and vasoconstricting substances produced by (or acting on) the endothelium. "Endothelial dysfunction is not only characterized by reduced NO bioavailability and another important fact is the increased expression of NOX1, NOX2 and NOX5, associated with inflammation, and reduced production of vasculature-protective biomolecules, such as the product catalyzed by NOX4." (PMID 36467706, 2022). "In conclusion, using an in vivo approach, our study demonstrated that the HIV transactivator protein Tat contributes to HIV-associated endothelial dysfunction via promoting adipose mass loss, and leptin level reduction leading to an upregulated expression of Nox1 and NoxA1." (PMID 34681637, 2021). "ROS production by Nox1 is the main cause of NO depletion and consequent endothelial dysfunction." (PMID 34681637, 2021). "Here, we claimed indirect relationship between Tat and Nox1-mediated impairment of vascular function by the fact that chronic Tat treatment, but not acute treatment, promoted the expression of ROS-producing enzymes Nox1 and its coactivator and caused endothelial dysfunction." (PMID 34681637, 2021). "Previously we showed that upregulation of NOX1 in endothelial cells (EC) of db/db mice drives endothelial dysfunction, but a role for NOX1 in PLY-induced lung injury, especially in diabetic conditions, has not yet been described." (PMID 41897422, 2026). "NADPH oxidases (NOXs), particularly NOX1, NOX2, and NOX4, are major sources of ROS in PH, driving endothelial dysfunction, PASMC proliferation, and vascular remodeling, all hallmarks of PAH progression." (PMID 40498015, 2025). "In a previous study, it was demonstrated that vascular NOX1 was of importance for RBC-mediated endothelial dysfunction in T2D." (PMID 40111409, 2025). "The increased production of ROS by NADPH oxidase such as NOX-1 and the subsequent reaction of ROS with NO have been described as key mechanisms of endothelial dysfunction." (PMID 37372034, 2023). "Nox1, and especially Nox2, trigger an oxidative stress response in the renal cortex, which generates endothelial dysfunction in the nearby arteries." (PMID 35954150, 2022). "We demonstrated, for the first time to our knowledge, that HIV protein Tat plays a critical role in the viral infection-induced endothelial dysfunction via elevation of Nox1 expression and reduction in adipokine leptin secretion." (PMID 34681637, 2021). "Inhibition of ROS production with GKT771 fully restored endothelial function in Tat-treated mice demonstrating the mediating role of Nox1 in the endothelial dysfunction evoked by Tat." (PMID 34681637, 2021). "Nox1, Nox2 and Nox5 promote endothelial dysfunction, inflammation and apoptosis in the vessel wall through the generation of superoxide." (PMID 34571964, 2021). "Nonetheless, the specific role of NOX1 in mediating endothelial dysfunction was further corroborated by rejecting the notion of cross-talk between NOX1 and NOX2 in a p47phox-NOXO1 double-KO mouse model." (PMID 31382355, 2019). "Although the importance of Nox1-derived ROS in endothelial dysfunction is well established, the precise mechanisms controlling Nox1 protein stability under disturbed shear stress remain unclear." (PMID 40313652, 2025). "To further investigate the mechanisms by which PFKFB3 contributes to endothelial dysfunction and decreased NO bioavailability, we transduced HAECs with NOX1 adenovirus (in addition to its coactivators NOXA1 and NOXO1) and either GFP (control) or wt-, cyt-, or KD-PFKFB3." (PMID 40002359, 2025). "However, it was difficult to prove that NOX1 is the prominent source of endothelial dysfunction because there were other concurrent observations, such as eNOS uncoupling and xanthine oxidase overexpression." (PMID 39064844, 2024).
endothelial dysfunction (continued). "HFHSD-LE2KO increased aortic superoxide levels, which might be caused by NOX1 and NOX4 upregulation, and the endothelial dysfunction caused by the decreased eNOS phosphorylation at Ser1179." (PMID 35955653, 2022). "Therefore, we sought to determine whether HIV-regulatory protein Tat mediates HIV-induced endothelial dysfunction via NADPH oxidase 1 (Nox1)-dependent mechanisms." (PMID 34681637, 2021). "Moreover, they illuminate Nox1 and TSP1-CD47 axis as attractive therapeutic targets for the treatment of non-healing diabetic wounds and various cardiovascular disorders associated with endothelial dysfunction and reduced angiogenic activity." (PMID 30720765, 2019). "The expression of endothelial dysfunction markers VCAM1, MMP9, and NOX1 in the lactate-treated group was significantly elevated, as indicated by the RT-qPCR." (PMID 41213933, 2025). "RT-qPCR demonstrated that SERPINE1 knockdown significantly downregulated endothelial dysfunction markers, including VCAM1, MMP9, and NOX1." (PMID 41213933, 2025). "NOX-driven oxidative stress (NOX1, NOX2, and NOX4) also plays a key role in Group 2 Group 3, and Group 4 PH, contributing to endothelial dysfunction, myocardial fibrosis, and structural remodeling of the right ventricle." (PMID 40498015, 2025). "NOX1 and NOX2 produce O2•− which mediates Ang II-induced oxidative stress, endothelial dysfunction, and exaggerated renal tubular salt transport." (PMID 39765782, 2024). "We observed endothelial dysfunction in pristane-induced SLE mice, exhibiting impaired endothelium-dependent vasodilation, upregulated NOX-1 production, and imbalanced eNOS activation, according to other authors." (PMID 37372034, 2023). "In conclusion, it is clear that hyperglycemia and T2D are strong stimulators of NOX1- and NOX2- dependent endothelial dysfunction." (PMID 31382355, 2019). "Furthermore, PFKFB3 enhanced the activities of NOX1 and NOX5, which are major contributors to endothelial dysfunction." (PMID 40002359, 2025). "In general, O2•− production by plasma membrane NOX1, NOX2, and NOX5 is pro-hypertensive by reducing NO bioavailability and promoting eNOS uncoupling, endothelial dysfunction, inflammation, transactivating epidermal growth factor receptor, cell proliferation/migration and apoptosis." (PMID 39765782, 2024). "In one study, NOX4, but not NOX1 or NOX2, is implicated in septic manifestations of acute lung injury and endothelial dysfunction." (PMID 38966542, 2024). "Our findings suggest that ApoE−/− mice develop endothelial dysfunction in the aorta by increased oxidative stress via the involvement of LOX-1, NOX1, and NOX2, whereas NOX4 may participate in media remodeling." (PMID 37873768, 2023). "Conversely, the expression of NOX1 and NOX2 proteins exhibited upregulation specifically within the endothelium of the ApoE−/− mouse aorta, implying their involvement in the generation of ROS and subsequent endothelial dysfunction." (PMID 37873768, 2023). "NOX1, NOX2 and NOX5 are characterized by their direct involvement in the onset of inflammation, apoptosis and endothelial dysfunction, while NOX4, by contrast, is characterized as an important vasoprotective agent, involved in the suppression of cell death pathways and increased NO bioviability." (PMID 36467706, 2022). "Dh404 significantly attenuated endothelial dysfunction in diabetic Akita mice characterized by reduced contraction in response to phenylephrine and the downregulation of inflammatory genes (VCAM-1, ICAM-1, p65, IL-1β) and pro-oxidant genes (Nox1 and Nox2)." (PMID 28253885, 2017). "Mice lacking NOX1, NOX2, NOX4, or p47phox display less endothelial dysfunction and severe HTN when exposed to acute Ang II infusion." (PMID 39765782, 2024). "Mice lacking a specific NOX isoform or subunit, either NOX1, NOX2, NOX4, 22phox, p47phox, or NOXA1, exhibit less endothelial dysfunction and less severe HTN induced by acute Ang II infusion." (PMID 39765782, 2024).
endothelial dysfunction (continued). "Hyperglycemia produces oxidative stress, upregulating endothelial NOX1/O2•−, but not NOX2, mediated reduction in NO bioavailability, eNOS uncoupling and endothelial dysfunction, and generation of pro-inflammatory/pro-fibrotic factors." (PMID 39765782, 2024). "Also, immunoreactivity to LOX-1 and NOX2, but not to NOX1 or NOX4 was elevated in retinal vessels of ApoE-/- mice, suggesting that a mechanism involving LOX-1, NOX2, and ROS may be involved in mediating endothelial dysfunction." (PMID 31781340, 2019).
liver fibrosis (27 papers, 2012 to 2025). "In an earlier study, inhibition of NOX1/4 axis has been shown to potently mitigate and attenuate liver fibrosis and associated oxidative stress." (PMID 37808009, 2023). "Pre‐clinical studies demonstrate that the effects of genetic NOX1/4 deficiency are consistent with those of setanaxib in human liver cells and animal models of liver fibrosis." (PMID 36658776, 2023). "Recent observations have demonstrated that the activity of the Rac1 protein causes the overproduction of ROS-induced NOX1 activation a then increased HSCs activity, which is thought to play a detrimental role in carbon tetrachloride-induced liver fibrosis." (PMID 32395205, 2020). "In an in vitro liver fibrosis model, OO was able to downregulate NOX1,2, and by this way the production of ROS by HepG2 cells." (PMID 39691690, 2024). "This is consistent with observations of suppressed ROS generation, HSC activation and liver fibrosis in NOX1 knockout (KO) mice compared with wild‐type (WT) mice." (PMID 36658776, 2023). "While there is evidence that NOX1/4 are important in progressing liver fibrosis, the cell‐type‐related functional differences of NOX1/4 in fibrotic pathologies must be considered." (PMID 36658776, 2023). "Setanaxib has been shown to replicate the hepatoprotective effects seen in multiple NOX1/4 KO models of liver fibrosis." (PMID 36658776, 2023). "Similar to complications in vascular smooth muscle cells, NOX1 also plays a role in tissue fibrosis, including liver fibrosis and pulmonary fibrosis." (PMID 37134122, 2023). "Yet other studies have shown that systemic NOX1/4 inhibition with GKT137831 can repress liver fibrosis induced by bile duct ligation or CCl4 treatment." (PMID 38060313, 2023). "In a study employing the models of carbon tetrachloride and bile duct ligation-induced liver injury in mice, NOX1 was identified as the NOX isoform related to hepatic fibrosis due to its proliferation-inducing effect in HSCs." (PMID 35740032, 2022). "Hepatocytes also express NOX isoforms, including NOX1, NOX2 and NOX4, which have been implicated in critical steps in initiating liver fibrosis, including hepatic stellate cell activation and hepatocyte apoptosis." (PMID 35740948, 2022). "In vivo experiments confirmed that dual‐targeting treatment with GKT137831, a well‐established NOX1/4 inhibitor, remarkably attenuated liver fibrosis." (PMID 35386842, 2022). "In experimental models, both the deficiency of NOX1 or NOX4 as well as the application of the dual NOX1/4 inhibitor GKT137831 was effective in attenuation of carbon tetrachloride-induced liver fibrosis." (PMID 34025430, 2021). "Hepatic fibrosis and ROS generation were attenuated in both NOX1 and NOX2 (gp91phox) null mice after CCl4 injection or bile duct ligation." (PMID 34071467, 2021). "Once Rac1 becomes activated, it incites the activation of NOX1 in which the activated NOX1 facilitates the conversion of HSCs into MF cells, subsequently leading to hepatic fibrosis." (PMID 32395205, 2020). "Our results showed that atorvastatin treatment notably ameliorated hepatic fibrosis, accompanied by the decreased expression of NOX1, Rac1-GTP, and Rac1 in a rat model of BDL." (PMID 32395205, 2020). "PTP1B-depleted hepatocytes showed resistance to TGF-β through the activation of NADPH oxidase 1; moreover, hepatic fibrosis in response to cholestatic liver injury was ameliorated by the same mechanism." (PMID 32760098, 2020). "Currently both NOX1 and NOX4 and CYP2E1 are implicated in development of inflammation and liver fibrosis, whereas pharmacological inhibitors of these enzymes have been shown in vivo to prevent hepatocyte death and attenuate fibrosis progression." (PMID 27200149, 2016). "Previous studies demonstrated that GKT137831, a dual NOX1/4 inhibitor, attenuated liver fibrosis in mice as well as pro-fibrotic genes in hepatic stellate cells (HSCs) as well as hepatocyte apoptosis." (PMID 26222337, 2015).